CAST (calpastatin)
Diseases named in the same sentence as CAST in open-access papers (continued):
Sharing a sentence is not in itself a finding about the gene and the disease.
pulmonary arterial hypertension (2 papers, 2019 to 2023). Pulmonary arterial hypertension (PAH) is a group of diseases characterized by mean pulmonary artery pressure >20 mmHg and elevated pulmonary arterial resistance leading to right heart failure. "Calpastatin is also a secreted molecule found in the synovial fluid of RA and OA patients, plasma of patients with pulmonary arterial hypertension, and exosomes from luminal fluid of ovine uterus." (PMID 36902150, 2023). "Calpastatin, the protein encoded by CAST, has an inhibiting effect on calpain and has been evoked in the progression of pulmonary hypertension." (PMID 31417607, 2019). "Interestingly, the differential expression of CAST and MCTP2, found in the present study, could be linked with two pathological phenotypes, pulmonary hypertension and overweight, both of which associated with CMS, as shown in the present study." (PMID 31417607, 2019).
sarcopenia (2 papers, 2022 to 2025). Progressive decline in muscle mass due to aging which results in decreased functional capacity of muscles. "CAST overexpression partially or completely prevented these alterations, highlighting a functional link between CAPN activity and CKD-associated sarcopenia." (PMID 41369335, 2025). "The involvement of CAPNs in CKD-related sarcopenia was assessed using mice that overexpressed the CAPNs endogenous inhibitor, calpastatin (CAST)." (PMID 41369335, 2025).
Sepsis (2 papers, 2010 to 2022). Sepsis is defined as life-threatening organ dysfunction caused by a dysregulated host response to infection. "Growing evidence suggests that the calpain/calpastatin system plays a critical role in the association between sepsis and multi-organ system dysfunction." (PMID 36160853, 2022). "Finally, one study has suggested that skeletal muscle calpain activation in sepsis is secondary, at least in part, to loss of activity of calpastatin, the endogenous calpain inhibitor." (PMID 20233404, 2010).
alcohol dependence (1 paper, 2013). Physical and psychological dependence on alcohol. "In a previous GWAS study, the SNP rs13160562 near CAST was discovered to besignificantly associated with alcohol dependence." (PMID 23876401, 2013).
ampullary carcinomas (1 paper, 2012). "In the bile duct and ampullary cancer cohort, low cytoplasmic calpastatin expression was associated with adverse overall survival (P=0.012), which remained significant in multivariate analysis (P=0.037)." (PMID 23140395, 2012). "When the ampullary and bile duct cohort was separated to cancers of the ampulla and cancers of the proximal and distal bile duct, low calpastatin expression was associated with survival in the ampullary cancers only (P = 0.043)." (PMID 23140395, 2012). "In the bile duct and ampullary carcinomas an association was observed between high cytoplasmic calpastatin expression and patients aged above 60 years (χ2=4.376, d.f.=1, P=0.036)." (PMID 23140395, 2012). "In bile duct and ampullary carcinomas an association was observed between cytoplasmic calpastatin expression and patient age (P = 0.036), and between nuclear calpastatin expression and increased tumour stage (P = 0.026) and the presence of vascular invasion (P = 0.043)." (PMID 23140395, 2012). "The expression of calpain-1, calpain-2 and calpastatin cytoplasmic and nuclear expression was tested to determine associations with clinicopathological criteria in the pancreatic and the grouped bile duct and ampullary cancers." (PMID 23140395, 2012). "The aims of the current study were to investigate the expression levels of calpastatin, and of the catalytic subunits of μ-calpain and m-calpain in tumours from pancreatic, bile duct and ampullary cancer patients." (PMID 23140395, 2012). "In the bile duct and ampullary carcinomas calpain-1 expression had a statistically significant correlation with cytoplasmic calpastatin expression (r = 0.425, P < 0.001) and nuclear calpastatin expression (r = 0.295, P = 0.002), but not with calpain-2 expression." (PMID 23140395, 2012).
aneurysm (1 paper, 2024). Bulging or ballooning in an area of an artery secondary to arterial wall weakening. "Recently, it has been demonstrated that the expression of calpain was increased in aneurysm tissues obtained from Marfan syndrome patients, whereas calpastatin was decreased." (PMID 39590217, 2024).
Aortic Rupture (1 paper, 2025). The tearing or bursting of the wall along any portion of the AORTA, such as thoracic or abdominal. "As expected, calpastatin overexpression significantly reduced mortality associated with aortic rupture." (PMID 40171827, 2025).
Ataxia (1 paper, 2011). Ataxia refers to impaired coordination of voluntary muscle movement. "Conversely, several mice displayed a weak ERP, as evidenced by a body temperature greater than 34°C and mild walking ataxia score, despite retaining homozygous CAST/Ei alleles over a significant fraction of the critical region." (PMID 22241984, 2011).
atherosclerosis (1 paper, 2014). A disease characterized by the build-up of fatty material and calcium deposition in the arterial wall resulting in partial or complete occlusion of the arterial lumen. "We detected one locus on Chromosome 6 for atherosclerosis that maps within the 95% confidence interval of a previously reported QTL, Ath37, which was identified in studies using sub-congenic mice between C57BL/6J and CAST/EiJ." (PMID 25344410, 2014).
Atrophy (1 paper, 2008). Any weakening or degeneration, especially through lack of use. "Since NF-H, MAP2 and myelin basic protein (MBP) are substrates of calpain, and calpain is known to be involved in Aβ-induced axonal atrophy, expression levels of calpain and calpastatin were measured." (PMID 18706097, 2008).
blastomycosis (1 paper, 2022). Blastomycosis is a rare infection that may develop when people inhale a fungus called Blastomyces dermatitidis, a fungus that is found in moist soil, particularly where there is rotting vegetation. "In this work, we describe wide natural variation in both primary and acquired resistance to experimental pulmonary blastomycosis in eight founder strains, including 129, A/J, BL/6, CAST, NOD, NZO, PWK, and WSB of the Collaborative Cross collection, and the inbred DBA strain." (PMID 35089087, 2022).
Cachexia (1 paper, 2023). Severe weight loss, wasting of muscle, loss of appetite, and general debility related to a chronic disease. "An in vitro cachexia model using liver cancer cells and a C26 colon cancer study demonstrated that Calpain-1 was highly upregulated in these cells, which was opposite to the calpastatin level, and the Ca2 + -dependent proteolytic pathway was highly activated in the C26 cachexia rat model." (PMID 37217930, 2023).
celiac disease (1 paper, 2019). An autoimmune genetic disorder with an unknown pattern of inheritance that primarily affects the digestive tract. "On the other hand, the top non-HLA DMRs in celiac disease mapped to genes related to the immune response, including NLRC5 and TMEM105 in the epithelial fraction, and CAST and HOXC4 in the immune compartment." (PMID 30718669, 2019).
Cerebral ischemia (1 paper, 2023). Restriction of arterial blood supply to the brain associated with insufficient oxygenation to support the metabolic requirements of the tissue. "CAST expression has been shown to have a neuroprotective effect on cerebral ischemia." (PMID 36855067, 2023).
clear-cell carcinoma (1 paper, 2019). "High calpastatin expression was associated with younger patients (χ2 = 4.955, df = 1, P = 0.026) and high-grade serous carcinoma (HGSC) (χ2 = 17.403, df = 5, P = 0.004) whilst low calpastatin expression was linked with clear-cell carcinoma (CCC)." (PMID 30448882, 2019).
colon cancer (1 paper, 2020). "For this purpose, we compared the expression levels of CAPN1, CAPN2, CAPNS1 and CAST in different cell lines and chose human HCT116 colon cancer cells." (PMID 33078830, 2020). "HCT116 have increased levels of CAPN2 in comparison with other colon cancer cell lines, and we also confirmed that protein levels of CAPN1 and CAPN2 are significantly higher than those in HeLa or HEK293 cells while the amount of CAST is moderate." (PMID 33078830, 2020).
cyst (1 paper, 2015). A sac-like closed membranous structure that may be empty or contain fluid or amorphous material. "We have also generated a derivative congenic line with a refined CAST-derived Mpkd1-2 interval and demonstrated its dominantly-acting disease-modulating effects (e.g., 4.2-fold increase in total cyst area; p<0.001)." (PMID 26295839, 2015).
demyelinating disease (1 paper, 2022). A broad group of disorders that affect the myelin sheaths that cover the neurons. "Our results suggest that the calpain-calpastatin system has putative roles in myelination and demyelinating diseases of peripheral nerves." (PMID 36499770, 2022). "As a first step in examining calpains’ potential role in peripheral demyelinating diseases, we here characterize the calpains and calpastatin during postnatal development, in a chronic model when normal myelination is disrupted, and in an acute demyelinating model." (PMID 36499770, 2022).
E. coli infection (1 paper, 2020). "E. coli infection resulted in the upregulation of the genes encoding proteases, which participate in the degradation of ECM, namely, ADAM10 (logFC of 2.62), ADAM17 (logFC of 8.75), MMP9 and MMP14 (both with a logFC of 2.58), CAPN7 and CAST (both with logFC of 2.20)." (PMID 32234079, 2020).
Erythema (1 paper, 2020). Redness of the skin, caused by hyperemia of the capillaries in the lower layers of the skin. "In this study we wanted to evaluate if CAST/EiJ mice could serve as a suitable model to study VARV infection and whether the presentation of the subjective clinical signs (including reduced grooming, weight loss, decreased activity, ocular and nasal swelling, and erythema) were dose dependent." (PMID 31593747, 2020).
HCMV infection (1 paper, 2019).
Hyperglycemia (1 paper, 2015). An increased concentration of glucose in the blood. "Given the very recent study reporting that overexpression of calpastatin improved EDHF-mediated ED in the aorta of mice with hyperglycemia." (PMID 26120352, 2015).
hyperhomocysteinemia (1 paper, 2025). A serious metabolic condition caused by mutations in the MTHFR gene, medications, or nutritional deficiency. "In models of MASLD induced by hyperhomocysteinemia, CAST reduction was associated with increased calpain activity, which resulted in the degradation of the inhibitor kappa B alpha (IκBα)." (PMID 41468440, 2025). "Hyperhomocysteinemia also induces MASLD associated with increased calpain activity and reduced CAST levels." (PMID 41468440, 2025).
Infertility (1 paper, 2024). "Since further backcrossing of the Kif18agcd2 allele onto the CAST genetic background ultimately leads to more pronounced infertility, it is likely that multiple divergent CAST alleles with additive or epistatic interactions ultimately exacerbate germ cell depletion." (PMID 39677807, 2024). "Subsequent backcrossing of F2 mice to the CAST background increased the penetrance of infertility to 90%, while subsequent backcrossing to B6 decreased the penetrance to just over 37%." (PMID 39677807, 2024). "We found that CAST mice, which exhibit high penetrance of infertility in the absence of Kif18a, had significantly higher expression of Apc7 in juvenile and adult testicular tissue, as well as reduced expression of Apc5 in fetal ovarian tissue compared to B6 mice." (PMID 39677807, 2024).
inflammatory breast carcinoma (1 paper, 2016). An advanced, invasive breast adenocarcinoma characterized by the presence of distinct changes in the overlying skin. "Perhaps the most interesting observation is that of calpastatin expression, whereby high expression is associated with improved survival of inflammatory breast cancer and high expression is associated with adverse survival of non-inflammatory breast cancer." (PMID 27323818, 2016). "This study demonstrates that high calpastatin expression in the diagnostic core biopsy was significantly associated with improved survival in patients with inflammatory breast cancer, while the reverse was observed in non-inflammatory cases." (PMID 27323818, 2016).
invasive breast carcinoma (1 paper, 2016). A carcinoma that infiltrates the breast parenchyma. "In early invasive breast cancer expression of calpain-1, calpain-2 and their inhibitor, calpastatin, have been associated with clinical outcome and clinicopathological factors." (PMID 27323818, 2016).
ischemia (1 paper, 2022). A hypoperfusion of the BLOOD through an organ or tissue caused by a PATHOLOGIC CONSTRICTION or obstruction of its BLOOD VESSELS, or an absence of BLOOD CIRCULATION. "Previous studies have shown that calpastatin is downregulated in heart and brain tissue after ischemia-reperfusion injury." (PMID 35723325, 2022). "Overexpression of calpastatin and thus secretion could potentially have a protective effect against IRI; and targeting calpains during NMP could possibly protect the kidney against ischemia." (PMID 35723325, 2022).
mood disorder (1 paper, 2020). A cognitive disorder a disturbance in which the person's mood is hypothesized to be the main underlying feature. "The results of the sucrose preference test suggest that CAST KO dams are susceptible to pregnancy and postpartum mood disorder, which increases the risk for pup neglect." (PMID 32251313, 2020).
multiple sclerosis (1 paper, 2021). A progressive autoimmune disorder affecting the central nervous system resulting in demyelination. "Further analysis of diseases and functions found that in comparison with B6, CAST show a downregulation in pathways relevant to “multiple sclerosis,” “inflammatory demyelinating disease,” and “extravasation of cells”." (PMID 33567283, 2021).
Myocardial fibrosis (1 paper, 2015). "Overexpression of CAST significantly reduced the infarct size (P < 0.01) and blunted MI-induced interventricular hypertrophy, global myocardial fibrosis and collagen I and collagen III deposition, hypotension and hemodynamic disturbances at 21 days after MI." (PMID 25786109, 2015).
nasopharyngeal carcinoma (1 paper, 2020). A carcinoma arising from the nasopharyngeal epithelium. "For example, the endogenous inhibitor of CAPN protein, calpastatin, is downregulated in nasopharyngeal carcinoma." (PMID 32382656, 2020).
neuropathy (1 paper, 2022). A disorder affecting the nervous system that manifests with pain, tingling, numbness, and/or muscle weakness. "To examine the calpain-calpastatin system in the inherited neuropathy with dysmyelination, we collected sciatic nerves from wild-type (WT) and Tr-J mice at 8 weeks of age." (PMID 36499770, 2022).
osteoporosis (1 paper, 2023). A condition of reduced bone mass, with decreased cortical thickness and a decrease in the number and size of the trabeculae of cancellous bone (but normal chemical composition), resulting in increased fracture incidence. "This novel osteocyte-secreted-calpastatin mechanism could be therapeutically leveraged to treat osteoporosis in women." (PMID 36902150, 2023).
Ovarian tumours (1 paper, 2012). "Ovarian tumours of the serous type were associated with high expression of calpastatin (χ2 = 23.755, d.f. = 4, P < 0.001), high calpain-1 (χ2=15.961, d.f. = 4, P = 0.003) and high calpain-2 (χ2 = 26.02, d.f. = 4, P < 0.001)." (PMID 22435971, 2012).
Parkinson disease (1 paper, 2013). A progressive degenerative disorder of the central nervous system characterized by loss of dopamine producing neurons in the substantia nigra and the presence of Lewy bodies in the substantia nigra and locus coeruleus. "The main finding of this study is a lack of a significant association between the CAST gene and late-onset sporadic Parkinson’s disease in the Han Chinese population." (PMID 23951044, 2013).
prostate carcinoma (1 paper, 2018). A carcinoma that arises from epithelial cells of the prostate gland. "Other proteins such as the androgen receptor (AR), which is required for growth in both androgen-sensitive and androgen-insensitive prostate cancer are cleaved by calpain in the presence of high Ca2+ concentrations due to the release of calpain from the calpain-CaM-calpastatin complex." (PMID 30319995, 2018).
protein misfolding diseases (1 paper, 2023). "Thus, in protein misfolding diseases or disorders characterized by abnormal Ca2+ regulation, strategies to limit the effects of calpain activation are primarily based on calpastatin." (PMID 36984009, 2023).
renal dysfunction (1 paper, 2020). "We found that endothelial-specific Capn4 knockout and calpastatin overexpression alleviated renal dysfunction in endotoxemic mice." (PMID 32346126, 2020).
retinal disease (1 paper, 2011). "Rationale for the retinal disease pathway was based on findings that genetic alterations specific to CAST/EiJ have been shown to be potentially involved in the development of age related macular degeneration (AMD)." (PMID 21779340, 2011).
retinitis pigmentosa (1 paper, 2023). Retinitis pigmentosa (RP) is an inherited retinal dystrophy leading to progressive loss of the photoreceptors and retinal pigment epithelium and resulting in blindness usually after several decades. "The remodeling of photoreceptors caused by CAST and ELKS ablation in the mature retina sheds light on the previously unknown mechanisms of retinitis pigmentosa, a retinal disorder, with both sporadic and inherited cases, characterized by the degeneration of rod photoreceptors." (PMID 37108413, 2023).
substance dependence (1 paper, 2015). The psychological or physiological need to take a substance in order to experience its effects or to avoid the effects of its absence. "However, it was not correlated to risks of substance dependence (scores of AUDIT-C, HSI, and CAST)." (PMID 25972826, 2015).
systemic lupus erythematosus (1 paper, 2025). An autoimmune multi-organ disease typically associated with vasculopathy and autoantibody production. "Moreover, RA patients develop calpastatin autoantibodies, and their incidence is higher than in other patients with systemic autoimmune diseases, such as systemic lupus erythematosus (SLE, 27%), polymyositis/dermatomyositis (24%), systemic sclerosis (38%), and overlap syndrome (29%)." (PMID 41294867, 2025).
Tremor (1 paper, 2015). An unintentional, oscillating to-and-fro muscle movement about a joint axis. "Furthermore, we show that overexpression of CAST in mice results in enhanced autophagy and improves locomotor function and delays tremor onset in a mouse model of HD, as well as decreasing the number of Htt aggregates seen in the brain." (PMID 25257175, 2015). "Overexpression of CAST delayed the age of onset of tremors in the HD mice." (PMID 25257175, 2015).
uremia (1 paper, 2025). A clinical syndrome associated with the retention of renal waste products or uremic toxins in the blood. "However, mice overexpressing CAST showed significantly reduced fibrotic areas and lower fibronectin expression, suggesting that CAST overexpression may delay uremia-induced fibrosis." (PMID 41369335, 2025).